INS (insulin)
Diseases named in the same sentence as INS in open-access papers (continued):
Sharing a sentence is not in itself a finding about the gene and the disease.
Insulin resistance (continued). "Homeostasis model assessment of insulin resistance (HOMA-IR) was used to evaluate insulin resistance (fasting serum insulin (μIU/ml) × fasting plasma glucose (mmol/L)/22.5)." (PMID 36462120, 2023). "Ip3r1 knockout in skeletal muscle improved glucose tolerance and insulin sensitivity of mice on a normal chow diet, but worsened insulin resistance in diet-induced obese mice." (PMID 36894534, 2023). "Acetate gavage treatment further reduced insulin sensitivity and aggravated insulin resistance in obese mice on a high-fat diet." (PMID 37686768, 2023). "Insulin sensitivity was also improved, as assessed by serum insulin levels, homeostasis model assessment of insulin resistance (HOMA-IR), intraperitoneal (i.p.)glucose tolerance tests and i.p. insulin tolerance tests." (PMID 37735236, 2023). "Our study shows that both insulin resistance and decreased insulin secretion were the mechanisms leading to the conversion to T2D." (PMID 37795366, 2023). "Glucose tolerance reflects the β-cell ability to offset insulin resistance by increased insulin secretion, and as long as this balance holds, glucose tolerance remains the same." (PMID 37929025, 2023). "In patients with T2D, insulin resistance, which affects insulin-sensitive tissues (e.g., adipose tissues, skeletal muscle, and the liver), is the central pathophysiological mechanism underlying T2D progression." (PMID 36714242, 2023). "Fe can be used as an oxidant to participate in the pathogenesis of GDM, its main function is to induce insulin resistance and interfere with insulin release from pancreatic beta cells." (PMID 38104073, 2023). "Pioglitazone, for example, has been investigated for its capacity to enhance insulin sensitivity and alleviate insulin resistance, thereby contributing to improved glucose utilization." (PMID 38186506, 2023). "The clinical onset of type 2 diabetes (T2D) occurs when pancreatic β-cells fail to secrete sufficient insulin to maintain normoglycemia in the face of insulin resistance." (PMID 36967785, 2023). "Fasting blood glucose, insulin, and insulin resistance levels were significantly increased in the case group compared to their baselines." (PMID 36843827, 2023). "It delves into how NADPH affects insulin secretion, influences insulin resistance, and plays a role in ferroptosis." (PMID 38203517, 2023). "The metabolic score for insulin resistance (METS-IR) was recently proposed as a non-insulin-based, novel index for assessing insulin resistance (IR) in the Western population." (PMID 36673809, 2023). "Combining both human and animal data, it becomes noteworthy that CLM visibly reduces FBG despite a decrease in blood insulin, due to improved insulin resistance." (PMID 36934269, 2023). "In 2011, a study was reported on the relationship between Mn intake and the level of glucose, insulin, and insulin resistance among 573 girls aged 8–13 in Spain." (PMID 37834407, 2023). "Tumor necrosis factor-α and interleukin (IL)-6 are derivatives of acute-phase proteins, including CRP, and both potentially contribute to insulin resistance by affecting intracellular insulin signaling." (PMID 37448125, 2023). "The role of IL-6 in inflammation in insulin target tissues, the pathogenesis of systemic insulin resistance, and increasing vascular permeability contributing to tissue damage have been reported." (PMID 37685858, 2023). "WKY HF had significantly increased fasting plasma glucose and insulin, which pointed to insulin resistance that was confirmed by the HOMA index." (PMID 36678151, 2023). "By protecting pancreatic β-cells, improving insulin resistance (IR), and enhancing insulin secretion, astaxanthin is said to lower blood glucose levels." (PMID 37755075, 2023). "Based on the HOMA-IR values, 8 out of 12 volunteers showed insulin resistance and 4 showed normal insulin sensitivity." (PMID 37469434, 2023).
Insulin resistance (continued). "It reduces insulin resistance and decreases blood glucose concentration by inhibiting gluconeogenesis and suppressing hepatic glucose production with improved peripheral tissue insulin sensitivity." (PMID 36819384, 2023). "While membrane transport via GLUT 4 is considered a primary site for insulin resistance, glucose phosphorylation is also a significant component of muscle insulin resistance." (PMID 37887696, 2023). "The failure of metabolic tissues to appropriately respond to insulin (“insulin resistance”) is an early marker in the pathogenesis of type 2 diabetes." (PMID 36808134, 2023). "Placental hormones and inflammatory mediators such as TNFα can affect the phosphorylation status of insulin signaling molecules in key metabolic organs and directly contribute to the development of insulin resistance." (PMID 37650554, 2023). "Experimental studies in mice and rats with type 2 diabetes and insulin resistance revealed that the up-regulation of bilirubin synthesis by induction of heme-oxigenase ameliorates glucose metabolism and insulin sensitivity in rodents." (PMID 38107514, 2023). "Recent studies showed a positive effect in the reduction in insulin resistance and improvement of insulin plasma levels through supplementation with calcitriol together with lifestyle modifications." (PMID 36902639, 2023). "T2D is induced by insulin resistance (IR) or impaired insulin action and pancreatic beta cell demise." (PMID 37754255, 2023). "In T2D, bodily tissues such as the muscles and fat also develop insulin resistance, in addition to often co-occurring underproduction of insulin." (PMID 37065506, 2023). "Insulin resistance leads to a compensatory increase in the synthesis and secretion of insulin by the beta cells of the islets of Langerhans and, accordingly, IAPP." (PMID 37833898, 2023). "It was reported that IL-1β disrupts insulin signaling and leads to insulin resistance in hepatocytes via decreasing IRS-1 expression." (PMID 37876013, 2023). "BC is correlated with insulin resistance and high insulin levels; one proposed mechanism by which CR inhibits tumor growth is its modulation of circulating levels of free IGF-1 in the serum, responsible for malignant transformation and neo-angiogenesis." (PMID 37960330, 2023). "These factors worsen insulin resistance by triggering different key steps in the insulin‐signaling pathway." (PMID 37408146, 2023). "The H animals not only showed compensatory hyperinsulinemia and insulin resistance, keeping similar glucose lower to the S group with higher levels of insulin, but also an increased β pancreatic function." (PMID 37447254, 2023). "This investigation found a positive correlation between plasma insulin levels and the synthesis rate of apoB48, indicating that insulin resistance is probably a factor." (PMID 38303975, 2023). "Results suggest that postprandial metabolomics profiles reflect mostly insulin actions, with changes derived from insulin resistance being more important with obesity but also being influenced by male sex and PCOS in women." (PMID 37736753, 2023). "Similar to depression, anxiety and stress can promote increased HPA activity, thereby promoting higher cortisol and arginine vasopressin secretion which subsequently impact insulin levels in the body and promote insulin resistance." (PMID 37823988, 2023). "Data revalidates and confirms that PP1γ regulates the neuronal insulin signaling and insulin resistance by dephosphorylating AKT2 via AKT-AS160-GLUT4 axis." (PMID 37085815, 2023). "With immune reconstitution, there is usually better insulin signaling at end organs which improves insulin resistance, a phenomenon that would have been expected on introduction of ART." (PMID 37689695, 2023). "Both can be activated by the insulin/insulin receptor substrate‐1 (IRS1) system in insulin resistance." (PMID 36333974, 2023).
Insulin resistance (continued). "The inhibition of Akt by ceramide impairs the insulin signaling pathway, further contributing to insulin resistance." (PMID 38203517, 2023). "Based on the result of the reviewed studies, curcumin improved fasting glucose levels, insulin, and homeostasis model assessment of insulin resistance (HOMA-IR) in a significant way." (PMID 36788534, 2023). "It is proven that inflammation contributes to the development of insulin resistance, thus increasing the requirement for exogenous insulin." (PMID 37180128, 2023). "For the predictor ‘basal insulin’, the outcomes were insulin resistance and/or dysregulation or laminitis." (PMID 37684968, 2023). "Insufficient β-cell compensation for maternal insulin resistance contributes to reduced insulin secretion and impaired glucose tolerance, characteristic of GDM." (PMID 38229396, 2023). "ITTs demonstrated that increasing doses of UCN2 gave rise to decreasing rates of glucose uptake in response to insulin injection, confirming that acute UCN2 causes insulin resistance in vivo." (PMID 37402735, 2023). "This produces obesity and hyperglycemia early in life; moreover, animals display insulin resistance and hyperglycemia due to reduced activity of insulin signaling and age-dependent degeneration in pancreatic β-cell function." (PMID 37759725, 2023). "These hormones can indirectly or directly antagonize insulin, resulting in insulin resistance and elevated blood glucose levels." (PMID 37118670, 2023). "Up-regulation of insulin secretion and insulin resistance results in elevated IGF-1 production and bioavailability, resulting in cell proliferation and tumor growth." (PMID 36617570, 2023). "Chronic-Cd exposure in drinking water elicits changes in insulin secretion and insulin resistance development." (PMID 36976988, 2023). "It is worth to note that such beneficial effects in insulin sensitivity were pronounced, especially among those subjects who presented the worse condition (i.e., frank insulin resistance) at baseline." (PMID 37237034, 2023). "Insulin resistance is a physiological condition characterized by reduced responsiveness of cells in the body to the effects of insulin." (PMID 37868469, 2023). "It has been demonstrated that hyposialylated IgGs activate the endothelial IgG receptor Fcγ receptor IIB (FcγRIIB), resulting in insulin resistance, whereas restored sialylation of IgGs maintained insulin sensitivity." (PMID 36907892, 2023). "Another interpretation of this result is that perioperative and postoperative stress responses deteriorate the impairment of insulin signaling in patients with insulin resistance, who already have severe metabolic syndrome." (PMID 38057801, 2023). "Wnt signals can alter important steps of insulin utilization within cells, leading to the progression of insulin resistance." (PMID 36875140, 2023). "Illustrating reduced insulin resistance, oral simufilam improved the response to insulin of mammalian target of rapamycin (mTOR) and suppressed mTOR’s basal overactivation in lymphocytes of AD subjects." (PMID 37762230, 2023). "Studies have revealed that the development of DKD, insulin resistance, and decreased insulin secretion are all directly related to increased metabolism of this route." (PMID 37781128, 2023). "Because of the overlapping sites of action of insulin and FGF23 in the kidneys, attempts have been made to evaluate the association of FGF23 with insulin resistance in patients with advanced stages of chronic kidney disease." (PMID 38139126, 2023). "Insulin resistance is characterized by a reduced ability of insulin to stimulate glucose uptake by adipose and muscle tissue, as well as to inhibit glucose synthesis and production in the liver." (PMID 37373485, 2023).
Insulin resistance (continued). "Insulin resistance decreases the utilization of insulin-mediated total body glucose in skeletal muscle, increases basal lipolysis in the adipose tissue, and increases hepatic glucose production and the secretion of very low-density lipoproteins in the liver." (PMID 37175645, 2023). "Blood lipids, uric acid, hepatic enzymes, creatinine, glycated hemoglobin, glucose, and insulin were measured in fasting blood samples, and the Homeostasis Model Assessment for Insulin Resistance was calculated." (PMID 37396186, 2023). "Phosphoinositide-3-kinase (PI3K) plays an important role in the metabolic actions of insulin and a mutation in the PIK3R1 gene has been associated with insulin resistance." (PMID 36269347, 2023). "Insulin resistance refers to a state in which the body’s insulin cannot effectively exert its normal physiological effects." (PMID 37065747, 2023). "To gain a better understanding of the role of TRPM7 in insulin resistance, we measured ex vivo insulin action." (PMID 36717580, 2023). "Free fatty acids also impede the inhibition of insulin-modulated glycogenolysis, which results in insulin resistance." (PMID 37242195, 2023). "This study mainly aims to further explore on the significant relations of COVID-19 infection with body fat distribution, changes in serum insulin, and homeostasis model assessment-estimated insulin resistance (HOMA-IR) levels before and after the infection." (PMID 36843827, 2023). "The onset of insulin resistance is initially offset by enhanced production and secretion of insulin." (PMID 36574297, 2023). "Several studies have reported on the dysfunction of insulin signalling pathway at various levels thus leading to poor glucose uptake, termed insulin resistance." (PMID 36860368, 2023). "Sarcopenia aggravates insulin resistance, as muscle is a primary tissue for peripheral insulin-mediated glucose uptake." (PMID 36713086, 2023). "The traditional approach to managing diabetes has focused on modifying insulin resistance and supplementing insulin through medications." (PMID 36771435, 2023). "Pathophysiology and mechanism of type 2 diabetes: Type 2 diabetes is distinguished by the presence of insulin resistance, wherein the cells within the body fail to adequately respond to the physiological effects of insulin." (PMID 37724233, 2023). "Both contribute to insulin resistance and impaired insulin metabolic signaling, which is crucial for normal endothelial functioning, which is explained below." (PMID 36986170, 2023). "Normal weight insulin resistant phenotype was characterized in 251 Japanese female university students using homeostasis model assessment-insulin resistance." (PMID 37217782, 2023). "The most likely reason for this is that vitamins can promote the secretion of pancreatic B cells, reduce insulin resistance by increasing insulin secretion, improve blood sugar in patients, and protect the central nervous system to a certain extent." (PMID 37046484, 2023). "The serum insulin 0’ and 120’ concentrations as well as insulin resistance increased during treatment." (PMID 37497348, 2023). "The protective function of M2 macrophages in insulin resistance can be adjudged from the findings that higher levels of inflammation, weight gain, and insulin insensitivity are noticeable in mice with impaired M2 polarization." (PMID 36718668, 2023). "Loss of LSEC fenestrations reduces the ability for insulin to pass through the endothelium and contributes to hyperinsulinemia, insulin resistance, and impaired hepatic insulin signaling." (PMID 37471420, 2023). "Recent studies have found that UA directly induces insulin resistance and insulin signaling impairment in vitro and in vivo." (PMID 37818085, 2023). "Insulin resistance means that the body's cells are less responsive to the insulin produced, increasing blood glucose levels." (PMID 37123774, 2023). "PYGM was reportedly involved in insulin and glycogen signaling pathways, insulin resistance and necroptosis." (PMID 37745699, 2023).
Insulin resistance (continued). "The analysis of pyruvate tolerance and insulin sensitivity indicated a reduced ability to promote hepatic gluconeogenesis as well as severe insulin resistance in aged mice." (PMID 36890357, 2023). "To investigate the expression differences of ZFYVE28 in insulin resistance, we utilized palmitic acid (PA)-treated HepG2 cells to imitate impaired insulin sensitivity." (PMID 37884540, 2023). "Impaired insulin function in T2DM causes the further manifestation of complications such as glucose intolerance and insulin resistance." (PMID 37715850, 2023). "Insulin levels increased progressively with time, and the mice exhibited insulin resistance and glucose intolerance under intravenous glucose challenge." (PMID 36982743, 2023). "This potential central insulin resistance indicated a small potential of insulin on the feeding switching function." (PMID 37929025, 2023). "Non-insulin-based insulin resistance (IR) indices serve as the indicators of metabolic syndrome (MetS) but have limited value for predicting clinical outcomes." (PMID 37255931, 2023). "When insulin resistance occurs, insulin demand rises, leading to hyperinsulinemia due to the compensatory increase in both cell mass and insulin secretion." (PMID 37047820, 2023). "Compared to the prediabetes group, vitamin D supplementation at 1000 IU/kg BW successfully lowered fasting blood glucose, plasma insulin, and insulin resistance, as shown by HOMA IR." (PMID 37324274, 2023). "L-acetylcarnitine is an intermediate metabolite in insulin resistance, which increases fatty acid oxidation during lipid metabolism and promotes fatty acid utilization when the body's response to insulin is reduced." (PMID 37929280, 2023). "These are major organs in insulin resistance, and as such, we assessed insulin levels and insulin resistance." (PMID 37047458, 2023). "While genes involved in insulin production have a greater influence on men, genes involved in peripheric insulin resistance have a greater influence on women." (PMID 37291636, 2023). "HOMA-IR was developed as a breakthrough model of the glucose-insulin feedback system in the homeostatic (overnight fasting) state and hepatic insulin resistance under these conditions is the major determinant of HOMA-IR." (PMID 36944955, 2023). "The results showed that germinated mung bean polyphenol extract can increase insulin sensitivity, reduce insulin resistance and repair the function of pancreatic beta cells in type 2 diabetic mice." (PMID 37077902, 2023). "We revised the insulin-dependent glucose uptake in the Topp model by setting the insulin sensitivity as a decreasing function of insulin level to represent hyperinsulinemia-induced insulin resistance." (PMID 36848379, 2023). "In response to maternal insulin resistance, pancreatic islets of the mother undergo adaptive changes in β-cell mass and function, accounting for basal and postprandial increases of insulin secretion in the blood." (PMID 38229396, 2023). "Insulin and Homeostatic Model Assessment for Insulin Resistance (HOMA-IR) also exhibited a significant decrease (19.69±1.81 vs. 8.98±1.09 mIU/L and 6.52±0.98 vs. 2.57±0.036 p < 0.05, respectively) in the postoperative period." (PMID 37965235, 2023). "Collectively, CRP shows inhibitory effects on the insulin signaling pathway, and increased CRP with age is a potential biomarker and cause of insulin resistance and NAFLD." (PMID 37893085, 2023). "Many studies including ours showed that ceramides play a crucial role in lipotoxicity-induced insulin resistance and demonstrated that downregulating de novo ceramide biosynthesis prevents their deleterious action on insulin signaling in peripheral tissues." (PMID 37178918, 2023). "Further, conditioned media with PCA from C2C12 cells enhanced glucose uptake, positively modulated insulin signaling pathways, and reversed insulin resistance in HepG2 and 3T3-L1 adipocytes." (PMID 37298440, 2023).